RN7SL160P (RNA, 7SL, cytoplasmic 160, pseudogene)
Gene: Miscellaneous RNA gene on chromosome 2 (70,965,584 to 70,965,867, forward strand). Ensembl gene ENSG00000241159.
Homologues: Orthologues: chimpanzee Metazoa_SRP (97% identical), macaque Metazoa_SRP (93% identical). Paralogues in human: RN7SL1 (85% identical), RN7SL2 (85% identical), RN7SL3 (84% identical), RN7SL444P (81% identical), RN7SL220P (81% identical), RN7SL147P (80% identical), RN7SL296P (80% identical), RN7SL769P (80% identical), RN7SL7P (80% identical), RN7SL45P (80% identical), RN7SL464P (80% identical), RN7SL804P (80% identical), and 705 more.